IL17RE (interleukin 17 receptor E)
Description:
Specific functional receptor for IL17C. May be signaling through the NF-kappa-B and MAPK pathways. May require TRAF3IP2 /ACT1 for signaling. May be a crucial regulator in innate immunity to bacterial pathogens. Isoform 2 and isoform 4 may be either cytoplasmic inactive or dominant active forms. Isoform 3 and isoform 5 may act as soluble decoy receptors.
Synonyms: FLJ23658
Tractability: Antibody: UniProt places it where antibodies can reach, with high confidence; its Gene Ontology location is reachable by antibodies, with high confidence; UniProt predicts a signal peptide or a membrane-spanning region. PROTAC: ubiquitination databases record sites on it.
Gene: Protein-coding gene on chromosome 3 (9,902,612 to 9,916,402, forward strand). Ensembl gene ENSG00000163701.
Subcellular location: Cell membrane (Isoform 1); Cytoplasm (Isoform 2); Secreted (Isoform 3); Cytoplasm (Isoform 4); Secreted (Isoform 5)
Pathways (Reactome):
Immune System: Interleukin-17 signaling
Gene Ontology:
Molecular function: protein binding; interleukin-17 receptor activity
Biological process: interleukin-17-mediated signaling pathway; positive regulation of cytokine production involved in inflammatory response; protein K63-linked ubiquitination; T-helper 17 type immune response
Cellular component: plasma membrane; cytoplasm; extracellular region
Genetic constraint (gnomAD): Loss-of-function variants: 44 observed, 72.02 expected, observed/expected ratio (o/e) 0.61, 90% interval 0.48 to 0.79. The upper end of that interval is the gene's LOEUF score, 0.79, which puts it in group 3 of 6, group 1 being the genes least tolerant of losing a copy. Missense variants: 847 observed, 778.96 expected, observed/expected ratio (o/e) 1.09, 90% interval 1.03 to 1.15. Synonymous variants: 371 observed, 315.74 expected, observed/expected ratio (o/e) 1.17, 90% interval 1.08 to 1.28.
Homologues: Orthologues: chimpanzee IL17RE (99% identical), macaque IL17RE (94% identical), dog IL17RE (79% identical), rabbit IL17RE (69% identical), rat Il17re (69% identical), mouse Il17re (68% identical). Paralogues in human: IL17RC (23% identical), IL17RA (12% identical), IL17RB (12% identical), IL17RD (10% identical).
Diseases named in the same sentence as IL17RE in open-access papers:
IL17RE is named in the same sentence as 25 diseases in open-access papers, as found by Europe PMC text mining. Sharing a sentence is not in itself a finding about the gene and the disease. The quoted sentences say what the papers report.
psoriasis (3 papers, 2021 to 2025). An autoimmune condition characterized by red, well-delineated plaques with silvery scales that are usually on the extensor surfaces and scalp. "Given that IL-17C mediates keratinocyte proliferation and epidermal thickening in experimental models of psoriasis and atopic dermatitis, we wondered about the function(s) of the IL-17C/IL-17RE axis in the healing of wounds infected with S. aureus." (PMID 34576717, 2021). "Thus, IL-17C/IL-17RE contributes to wound healing in infected wounds, but is detrimental in immune-mediated diseases, such as psoriasis." (PMID 34576717, 2021). "Therefore, our data are in agreement with the role of IL-17RA, IL-17RC, and IL-17RE in psoriasis, but we could highlight a differential expression pattern in the epidermis." (PMID 40243580, 2025). "We found that transcription levels of IL17A, IL17C, and IL17F were increased in psoriasis compared with normal skin, which was in parallel with their receptors IL17RA, IL17RC, IL17RD, and IL17RE." (PMID 36009523, 2022). "In the analysis of significantly expressed genes between psoriasis and normal skin, IL17RC was considered as the most significantly overexpressed gene among the IL17 family members, followed by IL17RD, IL17RA, IL17F, and IL17RE." (PMID 36009523, 2022).
autoimmune disease (2 papers, 2020 to 2023). A disorder resulting from loss of function or tissue destruction of an organ or multiple organs, arising from humoral or cellular immune responses of the individual to their own tissue constituents. "It has been shown that IL-17RE is highly expressed in Th17 cells and that the IL-17C/IL-17RE-axis enhances the expression of cytokine by effector Th17 cells in a in a model of autoimmune disease." (PMID 32641167, 2020). "However, IL17RE has also been found to be expressed on TH17 cells in addition to stromal cells and IL17RE signaling can amplify TH17 cell responses in autoimmune disease." (PMID 37111458, 2023).
asthma (1 paper, 2020). "As it has been shown that IL-17A and IL-17C both require IL-17RA for the induction of inflammatory mediators in target cells and IL-17C promotes Th17 cell responses we hypothesized that the specific IL-17C receptor IL-17RE has a function in OVA-induced experimental asthma." (PMID 32641167, 2020). "Because of the functional overlap between IL-17A and IL-17C and the corresponding receptor complexes IL-17RA/IL-17RC and IL-17RA/IL-17RE, we examined the function of IL-17RE in mouse models of OVA-induced experimental asthma and acute exacerbation thereof." (PMID 32641167, 2020).
autoimmune hepatitis (1 paper, 2020). Hepatitis caused by autoantibodies. "IL-17RE is also highly expressed by liver resident CD4+ T cells and natural killer T cells and augments T cell function in autoimmune hepatitis together with IL-17C." (PMID 32641167, 2020).
candidiasis (1 paper, 2015). Infection with the organism Candida. "Of the other IL-17 family members, we considered that IL-17C and its receptor IL-17RE were the most likely to be important in candidiasis, given the similarity of the IL-17A- and IL-17C-induced downstream gene profiles and their common propensity to act at mucosal surfaces." (PMID 25849644, 2015). "Surprisingly, however, we detected no role for the IL-17C/IL-17RE signaling axis in these forms of experimental candidiasis." (PMID 25849644, 2015).
colitis (1 paper, 2017). Inflammation of the colon. "Although IL17RE has been reported to be a functional receptor for IL17C as well as mediating the mucosal immunity in the small intestine of mice during acute experimental colitis, the overall function of IL17REL still remains unclear." (PMID 28886140, 2017).
cutaneous candidiasis (1 paper, 2015). Candidiasis of the skin manifested as eczema-like lesions of the interdigital spaces, perleche, or chronic paronychia. "In this study, we used the most widely accepted models of oral, dermal and cutaneous candidiasis, none of which revealed a role for IL-17C or IL-17RE in host defense." (PMID 25849644, 2015).
fungal infections (1 paper, 2015). "Similarly, there may be a role for IL-17C/IL-17RE signaling in other types of fungal infections." (PMID 25849644, 2015).
inflammatory bone diseases (1 paper, 2025). "In addition, SCSP modulates inflammatory cascades by attenuating IL-17 signaling, Toll-like receptor pathways, and key genes implicated in inflammatory bone diseases, such as Ccl2, Il17re, Fosl1, Mmp13, Ccl5, Tlr1, Il12b, and Atp6v1b1." (PMID 40926992, 2025).
intestinal tumor (1 paper, 2023). "In intestinal malignancies, IL17C binding to IL17RE stimulated TH17 cells to produce pre-tumorigenic cytokines and deficiency of IL17RE dramatically decreased intestinal tumor growth." (PMID 37111458, 2023).
Obesity (1 paper, 2020). Accumulation of substantial excess body fat. "The interleukin 17 receptor E and interleukin 22 receptor subunit alpha were highly expressed in the current study, which may indicate a higher level of IL-17, due to obesity and a high level of IL-22 for protection from obesity." (PMID 32899471, 2020).
skin inflammation (1 paper, 2024). "Finally, Zc3h12a expression correlated with measures of skin inflammation, such that Zc3h12a increased in KC-Tie2 mice compared with control animals and decreased in the absence of Il17c, Il17re, and Il17ra." (PMID 38470486, 2024).
systemic candidiasis (1 paper, 2015). "As shown, there was no apparent role for IL-17C or IL-17RE signaling in host defense against systemic candidiasis, as IL-17C-/- and IL-17RE-/- mice followed the same survival curve as littermate control mice." (PMID 25849644, 2015).
tauopathy (1 paper, 2024). Neurodegenerative disorders involving deposition of abnormal tau protein isoforms (tau proteins) in neurons and glial cells in the brain. "One of the top transcripts that increased with tauopathy but decreased with Nanoligomer treatment was Interleukin 17 Receptor E (IL17RE), which is also associated with the activation of NF-κB and cognitive dysfunction." (PMID 39068433, 2024).
tumor (9 papers, 2014 to 2025). "Studies have revealed that among these cytokines, the IL-17 family (IL-17A to IL-17 F) and their receptor (IL-17RA to IL-17RE) are involved in Th17 responses, and they can participate in pro-tumor or anti-tumor responses depending on their phenotype." (PMID 38515019, 2024). "Some of these biomarkers are immunosuppressive or have pro-tumor activity such as PD-L1, IL17RE, LAG-3, IDO-1, TIM-3 whereas others have antitumor activity such as CD8+ T-cells, OX40, CXCL9 and others have a mixed role such as IFN-G." (PMID 36612271, 2022). "Il17a and Il17re have similar pattern of expression: calcitriol decreased the expression in young mice in the early phase of tumor progression, whereas in old OVX mice the expression of both genes increased." (PMID 32257539, 2020). "The expression of two genes associated with Th17 cells is intriguing since the Il21 mRNA level decreased in tumour tissue from treated mice, whereas Il17re was increased." (PMID 31595196, 2019). "More importantly, IL-17 directly repressed expression and function of miR-192; and miR-192 sequentially targeted IL-17RA and IL-17RE, which binds the ligand IL-17 to function in tumor microenvironment." (PMID 25489847, 2014). "As a marker cytokine for TH17 cell subsets, IL17RE may help to reshape tumor microenvironment and tumor growth/survival." (PMID 34604392, 2021). "The NF-κB signaling pathway activates proinflammatory signals (such as TNF) through IL17RE and CRP, thereby promoting tumor growth in an inflammatory environment." (PMID 40989695, 2025). "Most importantly, interleukin-17 receptor e (IL17RE), interleukin-17 receptor c (IL17RC), and FGFR3, all involved in the regulation of tumor microenvironment (TME), were found in this group." (PMID 35641998, 2022). "In fact, these are well known indicators for poor prognosis and early tumor recurrence in patients with HCC, for instance, glypican 3, MicroRNA-29, hyaluronic acid, Ski-interacting protein, interleukin-6, VEGFR2, IL-17 and IL-17RE, G2890 N-glycan, GGT and miR-24-3p." (PMID 25970775, 2015).
infection (8 papers, 2018 to 2025). The state of being infected such as from the introduction of a foreign agent such as serum, vaccine, antigenic substance or organism. "Deficiency in IL-22 or IL-17 Receptor E (IL-17RE) led to enhanced mucosal damage after infection by pathogenic bacteria such as Citrobacter rodentium." (PMID 30543324, 2018). "Except for IL17RE, the transcription levels of all other cytokine receptors were significantly increased in response to infection." (PMID 35705998, 2022). "In mice IL17RE is the receptor for IL-17C, which has an essential role in host mucosal defense against infection and is critical for a successful immune response against bacterial infection." (PMID 32228433, 2020). "However, the HK expression of il17rd at 1 and 15 dpi was completely blocked, whereas that of il17re was significantly reduced at all the infection times." (PMID 38827125, 2024). "Expression of IL17re/IL17C is important in mucosal immunity against bacterial pathogens such as Citrobacter, and this cytokine previously reported to be upregulated in response to infection by a variety organism, including viruses, fungi, and bacteria." (PMID 33897648, 2021).
inflammation (2 papers, 2015 to 2020). Aberrant reaction of the microcirculation characterized by movement of fluid and leukocytes from the blood into extravascular tissues. "Since IL-17C and IL-17RE are expressed in the skin and have been shown to be pathogenic in mouse models of dermal inflammation, we hypothesized that the most likely setting in which the IL-17C/IL-17RE axis might participate in antifungal immunity would be in cutaneous C. albicans infections." (PMID 25849644, 2015).
immune system diseases (1 paper, 2018). "DEGs that enriched to “immune system diseases” played critical roles in cell-matrix communication (THY1, LVRN, LUM, TIMP3, SPOCK1, LGALS3BP, FAT2, and SERPINE2) as well as inflammation (IL1R2, CD22, PTGES, TNFSF10, IL2RB, C3, SERPING1, and IL-17RE)." (PMID 30131724, 2018).
IL17RE also shares sentences with these, for which no sentence is quoted: bacterial infection (1 paper); cancer (1); dermatitis (1); disseminated candidiasis (1); pheochromocytoma (1); retinal angiomas (1); rheumatoid arthritis (1).